FRMD7 (FERM domain containing 7)
Diseases named in the same sentence as FRMD7 in open-access papers (continued):
Sharing a sentence is not in itself a finding about the gene and the disease.
cocaine addiction (1 paper, 2020). "Twelve DEGs (Myct1, Gm21860, Ninj2, Fam183b, Lars2, Alkbh1, Fgf5, Frmd7, Tm6sf2, Wnt6, Batf3, and Clca1) were found to be regulated inversely among the overlap genes, which may be possible targets of RPA to disrupt the cocaine addiction process." (PMID 32489401, 2020).
neuritis (1 paper, 2023). A neuropathy arising from inflammation of one or more nerves. "Since the FRMD7 protein promotes neuritis lengthening and is expressed in the actin-rich distal ends of growth cones, it is thought to regulate cytoskeletal dynamics and modulate growth cone guidance primarily via Rho GTPase signaling." (PMID 36833273, 2023).
Stickler syndrome (1 paper, 2024). Stickler syndrome is an inherited vitreoretinopathy characterized by the association of ocular signs with more or less complete forms of Pierre-Robin sequence, bone disorders, and sensorineural deafness (10% of cases). "Exome sequencing identified 21 potential pathogenic variants of 13 genes in 20 of 75 (26.7%) probands, including genes for Stickler syndrome (COL11A1 and COL2A1; 6/20), FEVR (FZD4, LRP5, and TSPAN12; 5/20), and others (FBN1, GPR179, ZEB2, PAX6, GPR143, OPN1LW, FRMD7, and CACNA1F; 9/20)." (PMID 38243264, 2024).
genetic disorders (1 paper, 2023). "Such molecular genetic studies not only broaden the molecular spectrum associated with FRMD7 mutations in Pakistani families but also enhance our understanding of the molecular mechanisms involved in genetic disease." (PMID 36833273, 2023). "Overall, such molecular genetic studies expand our current knowledge of the mutations associated with the FRMD7 gene in Pakistani families with CIN and significantly enhance our understanding of the molecular mechanisms involved in genetic disorders." (PMID 36833273, 2023).
skin disorder (1 paper, 2021). Any deviation from the normal structure or function of the skin or subcutaneous tissue that is manifested by a characteristic set of symptoms and signs. "FRMD7 is putatively involved in fatty acid metabolism and has been associated with skin disorders, serving as a potential factor in differential susceptibility between sexes to DFTD." (PMID 34579650, 2021).
FRMD7 also shares sentences with these, for which no sentence is quoted: ocular albinism (2 papers); optic atrophy (2); Central hypothyroidism (1); epilepsy (1); foveal hypoplasia (1); myopia (1); parasitemia (1); Retinal dystrophy (1).